TIMP1 (TIMP metallopeptidase inhibitor 1)
Diseases named in the same sentence as TIMP1 in open-access papers (continued):
Sharing a sentence is not in itself a finding about the gene and the disease.
tumor (continued). "TIMP1 histoscore by cell type (tumor cell, other) was quantified using digital image analysis." (PMID 39789100, 2025). "Given the prominent roles of IL‐8 and TIMP‐1 in the interaction between endothelium and tumor spheroids, we hypothesized that these cytokines are key contributors to tamoxifen resistance in the TME." (PMID 39805002, 2025). "This incremental binding efficacy correlated with the strength of the effect of the glycosylation variants on tumor cell proliferation and survival, corroborating that the tumor-promoting cytokine-like effect of differentially glycosylated TIMP-1 was mediated by its interaction with CD63." (PMID 40345589, 2025). "Our results suggest that during epithelial differentiation, TIMP1’s sustained high expression may protect tumor epithelial cells from ECM detachment, thereby facilitating their proliferation and differentiation." (PMID 41187171, 2025). "Our data suggest that the I-pEMT-P program may remodel the stromal niche via TIMP1, influencing tumor progression and clinical outcomes." (PMID 40145096, 2025). "The relative contribution of these pathways may depend on tumor stage, microenvironmental stressors, and TIMP1 expression levels." (PMID 40185230, 2025). "Our observation of an inverse correlation between tumor cell TIMP1 expression tumor necrosis percentage aligns with this view, as TIMP1 may protect hypoxic cancer cells from dying." (PMID 39789100, 2025). "Additionally, TIMP-1 also exhibits anti-apoptotic properties, which can contribute to tumor cell survival under certain conditions." (PMID 39199626, 2024). "Interestingly, the extracellular matrix protein-encoding genes such as FN1, TIMP1, COL3A1, COL4A1, and COL2A1 were discovered in spatial cluster 8, regarded as tumor stroma tissues." (PMID 39257581, 2024). "TIMP-1 inhibits tumor cell proliferation, migration, angiogenesis, and apoptosis." (PMID 38333871, 2024). "Our cross-tissue study highlighting TIMP1 differential expression in the TME and its association with a gene signature indicative of peptide loading onto MHC-I molecules in tumor-draining LNs underscores a pivotal functional link for TIMP-1 in tumor immunogenicity." (PMID 38777826, 2024). "TIMP1 belongs to the tissue inhibitor of the metalloproteinases family of proteins and exerts anti-proteolytic activity on matrix metalloproteinases (MMPs), which is initially proposed to prevent tumor progression by inhibiting MMP activity." (PMID 38770133, 2024). "Of fact, it has been reported that the anti-tumor effect of MSC may be partly related to the activity of the TIMP-1 and TIMP-2." (PMID 38664697, 2024). "While the increase of TIMP-1 secretion by stimulated human DCs wasn’t statistically significant, it suggests a potential avenue for future studies, especially in conditions mimicking the tumor’s cytokine milieu or involving co-stimulatory immune signals." (PMID 38777826, 2024). "The results of gene expression analysis demonstrated a slight decrease in the expression of MMP-9 and an increase in the expression of TIMP-1 in tumorous samples compared to normal adjacent tissues, which correlates with an increase in the expression of these proteins." (PMID 39062015, 2024). "Likewise, intratumoral injection of Toxoplasma lysate antigen in CT26 tumor-bearing Athymic nude mice and euthymic mice reduced tumor growth and TIMP-1 level, a metastatic marker, in both mouse models." (PMID 39367471, 2024). "High expression of TIMP1 promotes stem cell-like traits in tumors by modulating epithelial–mesenchymal plasticity; cells with this phenotype act as senders, whereas other tumor cells act as receptors." (PMID 38280909, 2024). "In tumorous tissues, TIMP-1 also showed a slight decrease compared to healthy samples." (PMID 39062015, 2024). "Thus, levels of TIMP1 in the TME should correlate with immune biomarkers in the lymphoid tissues due to the role of activated tumor-resident DCs in antigen presentation." (PMID 38777826, 2024).
tumor (continued). "This preliminary observation led to testing whether specific subpopulations of DCs pertinent to tumor antigen presentation could manifest better TIMP-1 secretion in response to stimulus." (PMID 38777826, 2024). "Additionally, KLF4 inhibits the migration and invasion of tumor cells by suppressing biological enzymes like TIMP-1 and TIMP-2." (PMID 39000273, 2024). "One potential limitation of this study may be the unavailability of extensive in vivo studies that delve into the intricate mechanistic aspects of TIMP-1’s influence on tumor immunity." (PMID 38777826, 2024). "In this study, we firstly revealed that the level of some proteins (such as NRP2, TIMP1, ITGB2, ITGAM) associated with tumor metastasis promotion was decreased in the exosomes derived from MNDA knockdown M2 macrophages, which could be taken up by HCC cells." (PMID 38904028, 2024). "This dual role makes TIMP-1 a complex and multifaceted regulator in the tumor microenvironment." (PMID 39199626, 2024). "Monocytes present M1 and M2 features indicated by aberrant pro- and anti-inflammatory core TF regulatory loops, pro-differentiation, and reduction of cell cycle genes as well as expression of tumor- and metastasis-promoting factors, such as TIMP1 and EREG63,64." (PMID 37365178, 2023). "The mechanism of TIMP1 in regulating anoikis in the tumor microenvironment may provide insights for the design of new immunotherapies for ccRCC." (PMID 37688768, 2023). "The expression pattern of TIMP-1 and its molecular function in a tumor are conflicting." (PMID 37091145, 2023). "Interestingly, one year after tumor removal, TIMP1 expression was at a similar level in both histological subtypes of NSCLC." (PMID 37509417, 2023). "Preoperative TIMP1 expression level in peripheral blood may link to the GC stage, suggesting its potential application as a marker for tumor invasion and metastasis." (PMID 38041130, 2023). "Likewise, TIMP-1 is an MMP-inhibitor at the cancer periphery but is involved in tumor-induced angiogenesis in the pericytes." (PMID 36672169, 2023). "Immunohistochemical analysis showed that TIMP1/MMP9/CD44 ternary complex expression in primary tumor avatars paralleled an increase of the expression levels of TWIST, SNAIL in the xenograft metastasis, resembling the phenotypic landscape of PTC and ATC patient-derived primary and metastatic lesions." (PMID 36906579, 2023). "The role of TIMP-1 in tumor growth, invasion and metastasis remains controversial." (PMID 36690987, 2023). "In addition, JZL184 caused a dose-dependent regression of A549 tumor xenografts in athymic nude mice, which was associated with a decreased number of CD31-positive cells and upregulation of TIMP-1-positive cells in xenograft tissue." (PMID 37443791, 2023). "Moreover, when compared to normal renal cell lines, the expression of TIMP1 was markedly elevated in tumour cell lines, with the highest expression observed in the A498 cell line." (PMID 37688768, 2023). "We then used 3D matrix invasion assays to examine whether TIMP1 enhanced the invasive potential of fibroblasts, thereby promoting tumour expansion or extension by supporting MM cell translocation." (PMID 36768545, 2023). "Here, the 2-AG increase results from the inhibition of MAGL and leads to a reduction in the angiogenic capacities of endothelial cells in the tumor microenvironment via a CB1-dependent pathway, with increased TIMP-1 release from lung tumor cells being causative." (PMID 37443791, 2023). "All these data suggest that MM tumour burden affects the TIMP1 load in the BM." (PMID 36768545, 2023). "Thus, we observe the close involvement of the Timp1 gene and its first neighbors both in acute inflammation and its long-term consequences such as fibrosis development and tumor transformation." (PMID 36675165, 2023). "In the future, identification and obstruction of the tumor-promoting function of TIMP1 may be another method of antitumor treatment." (PMID 37014331, 2023).
tumor (continued). "Moreover, many evidences have shown that TIMP‐1 is also able to promote tumor cell proliferation and survival, and studies have shown that TIMP‐1 upregulation is associated with a worse outcome in patients with multiple tumors." (PMID 36560848, 2023). "Additionally, Timp1 knockdown decreases proliferation, migration and invasion of tumor cells of diverse origins." (PMID 36675165, 2023). "TIMP-1 can act in a tumor-supportive or tumor-suppressive manner." (PMID 36291767, 2022). "Saliva TIMP-1 was significantly higher in tumor patients compared to the control group (p = 0.013)." (PMID 36551979, 2022). "Therefore, the function and regulation of TIMP1 and Sp1 in immune cells can have a vital role in tumor pregression and aslo warrants further investigation." (PMID 35778451, 2022). "Elevated expression of MMP-1 and TIMP-1 in tumor tissue can predict invasiveness for PTC." (PMID 36551933, 2022). "Interestingly, the levels of CXCL-7, TIMP-1, sICAM-1 and l-selectin of the vehicle and Dox groups seemed to be equal, although Dox inhibited tumour progression." (PMID 34962450, 2022). "TIMP-1 was originally characterized as an endogenous inhibitor of metalloproteinases (MMPs) and known for its role in extracellular matrix remodeling, both of which are crucial for tumor invasion and metastasis." (PMID 36430649, 2022). "In addition to the contradictory role of TIMP1 in tumor growth and metastasis, very little is known about the secretion function of TIMP1." (PMID 36457117, 2022). "Outside of MMP9 inhibition, TIMP-1 may contribute to other tumor-supporting phenomena including enhanced proliferation and epithelial to mesenchymal transition." (PMID 35200382, 2022). "It is also likely that TIMP-1 plays different roles in different tumor/cell contexts." (PMID 36216799, 2022). "mRNA expression of Mmp9, Egfr and Hmox1 (tumor progression), Timp1 and Timp2 (inhibitors of metalloproteinases) and Hif1α (hypoxia) evaluated in lung homogenates was significantly augmented in LLC-challenged Igf1rfl/fl mice, remaining unaltered in CreERT2 mice." (PMID 35688943, 2022). "With the exception of its suppressive role against most of the known MMPs, as a cytokine and a key regulator of ECM degradation, TIMP1 has a variety of functions related to tumor microenvironment and progression, tumor cell proliferation, and antiapoptotic activity in cancer." (PMID 35685428, 2022). "In conclusion, suppression of DAPK1 may accelerate tumor growth and result in the upregulation of C3, TIMP-1, and AHSG expression and downregulation of KNG1 expression." (PMID 35935258, 2022). "Notably, IL1B, NDRG1 and TIMP1 act as drivers of ferroptosis, and their low expression in patients with poor prognosis implies a correlation between tumor cell resistance to ferroptosis mechanisms and poor prognosis." (PMID 36226170, 2022). "To investigate further the relationships between TIMP1 and the diverse tumor-infiltrating immune cells, we studied the correlations between TIMP1 expression levels and those of immune markers for various immune cells in GBM, STAD, HNSC, and LGG using the CORRELATION Module in the TIMER database." (PMID 35778451, 2022). "To determine whether TIMP1 is differentially expressed in cancer, we found that TIMP1 actually upregulated in the majority of tumor types in comparison to normal tissues in Oncomine database." (PMID 35778451, 2022). "In contrast, we discovered that active-form Rab37 increased autophagic activity and TIMP1 secretion, which led to suppression of lung cancer cell metastasis from the right lung to the left lung, as well as a decrease in tumor nodules." (PMID 36457117, 2022). "The tissue inhibitor of metalloproteinase 1 (TIMP-1) inhibits matrix metalloproteinases (MMPs) and thus may influence tumour growth and invasion." (PMID 35818030, 2022).
tumor (continued). "Although interest in TIMP1 has increased based on its role as a protein biomarker in various cancers according to findings in solid or liquid biopsies, its precise functional role as a tumour promotor has remained unclear." (PMID 35140332, 2022). "Finally, we observed a reduction in TIMP-1, which was able to promote tumor growth independently of its MMP inhibitory activity." (PMID 36140255, 2022). "TIMP1 was shown to be upregulated in EAC lesions when tumor cells invade into esophageal mucosa." (PMID 35328735, 2022). "Similarly, we discovered that TIMP1 was negatively in connection with tumor purity through the TIMER2.0 database, which suggested that TIMP1 was mainly derived from stromal cells rather than GBM cells." (PMID 35685428, 2022). "In this study, the use of serum and saliva as a potential source for the protein markers TIMP-1 and fHsp70 was analyzed, hereby assessing different aspects such as the difference between tumor patients and healthy subjects as well as the prognostic value of the markers." (PMID 36551979, 2022). "Furthermore, the expression comparison of FAPα versus Meflin or TIMP-1 in the same tumor of the 17 FFPE PDAC samples showed that higher-Meflin and/or higher-TIMP-1 than FAPα is involved in prolonged survival." (PMID 35773436, 2022). "Taken together, these results indicate that TIMP‐1 in hASCs could be involved in the process of drug penetration and resistance in our 3D tumor model." (PMID 35600659, 2022). "Whether TIMP‐1 expression is regulated by hypoxia in hASC‐co‐cultured tumor spheroids, and whether hypoxia‐related factors other than HIF‐1α might affect it remains to be elucidated." (PMID 35600659, 2022). "Interestingly, the stroma around the tumour tissues showed a preponderance of TIMP1 level in both the TC and IM of liver MET relative to that in primary CRC." (PMID 35140332, 2022). "TIMP-1 influences the tumor microenvironment through different pathways." (PMID 36551979, 2022). "SERPINE1 and TIMP1 promote the migration and invasion of tumor cells." (PMID 35464849, 2022). "Furthermore, recombinant fusion protein linking TIMP1 to glycosylphosphatidylinositol anchor enhances tumor sensitivity to doxorubicin." (PMID 34737677, 2021). "Considering MMP/TIMP expression, tumor budding showed a positive and significant association with MMP-11 (p = 0.029), MMP-14 (p = 0.024), and TIMP-1 (p = 0.021) expression by CAFs and MMP-14 expression by tumor cells (p = 0.034)." (PMID 33669393, 2021). "Similarly, TIMP1 can also activate cancer-related fibroblasts Cells (CAF) promote the growth of primary tumours." (PMID 35003085, 2021). "CCL2, CCL3, TIMP-1, and IL-13 are products readily found in an immune response that is driven by M2 macrophages, which correspond to a tumour growth-promoting phenotype that aids tumour cell proliferation, reduction of an antigen-specific immune responses, and increased angiogenesis." (PMID 33494138, 2021). "In addition, an immunohistochemical study of MMP-9, -11, and -14 TIMP-1 and -2 expression by cell types at the invasive tumor front was carried out." (PMID 33669393, 2021). "However, MMP-1, MMP-9 and TIMP-1 were more frequently expressed by stromal macrophages in BCC samples from immunocompetent individuals, emphasizing the role of the tumor microenvironment in BCC behavior in association with the patient’s immune status." (PMID 34204372, 2021). "MMP2 (log2 fold change = 7.47), MMP9 (log2 fold change = 3.63), and TIMP2 (log2 fold change = 2.66) displayed increased expression in the TME, while MMP13 (log2 fold change = −4.41) and TIMP1 (log2 fold change = −2.26) displayed increased expression in the HCC tumor." (PMID 33995488, 2021). "Interestingly, the analytical results showed high expressions of the MYC/CXCL8/TIMP1 oncogenes in tumor samples compare d to normal samples." (PMID 34440739, 2021).
tumor (continued). "However, interestingly, many studies have shown that TIMP-1 expression is also increased in several tumor types, and increased TIMP-1 expression was correlated with poor prognosis of different types of human cancers." (PMID 34502227, 2021). "In this study, overexpression of MMP13 and TIMP1 was observed in the HCC tumor cells." (PMID 33995488, 2021). "TIMP1 is thus closely related to tumor invasion and metastasis." (PMID 34109215, 2021). "Furthermore, relative to other TIMPs, widespread TIMP-1 increase can be observed in solid cancers as tumours progress." (PMID 33628641, 2021). "In PTC patients, 131I therapy almost halved the imbalance between MMP-9 and TIMP-1 and this decrease may reduce tumor cell viability and migratory potential." (PMID 34298820, 2021). "The present data suggest that CDV inhibits tumor growth in a multifactorial way, including direct cell lysis and reduction of angiogenesis and modulation of MMPs and their inhibitor TIMP-1, providing further support for the concept of its role in oncolytic therapies." (PMID 33808256, 2021). "Knocking-down IKKβ or Timp1 reduced tumour growth in xenografts." (PMID 34503110, 2021). "Furthermore, DH82-medium neoplasms displayed a smaller peripheral TIMP-1 immunopositive area than DH82-UV-CDVai (p < 0.0001) xenografts or untreated controls (p < 0.0001)." (PMID 33808256, 2021). "These novel findings further provided molecular insight into TIMP-1-mediated chemotherapy resistance involving glycolytic tumor metabolism and extracellular acidosis in addition to the previously characterized CD63/integrinβ1/FAK/PI3K/ERKs survival signaling pathways." (PMID 34685701, 2021). "In addition, increased expression of several genes in the TME known to drive expression of HCC tumor-derived TIMP1 and MMP13 was observed." (PMID 33995488, 2021). "CD82 was identified as a component of the cell surface TIMP1-interacting protein complex by directly binding to Timp1 amino-terminal region through its large extracellular loop domain and, it was shown to co-localise with Timp1 in cancer cell lines and tumour tissues." (PMID 34503110, 2021). "The correlation of increased TIMP-1 expression with a poorer prognosis in cancer patients made researchers question the roles that TIMP-1 could play in tumor progression, in addition to its inhibitory function of MMPs." (PMID 34502227, 2021). "Moreover, NFκB activation, a hallmark of the MES phenotype in gliomas, promotes the expression of a series of matrix regulators such as Serpine1, Plau (plasminogen activator, urokinase) and TIMP1, inducing tumor proliferation and growth." (PMID 32570988, 2020). "Notably, from the CTC gene expression signature, AR and TIMP1 were studied as potential targets to block tumor growth and dissemination in TNBC." (PMID 32012729, 2020). "It needs to be considered that higher levels of TIMP-1 expressed in tumor or stroma might be a result of MMP expression in cancer patients." (PMID 32466129, 2020). "Additionally, we generated zebrafish xenografts to in vivo analyze the impact of TIMP1 down regulation, finding again a significant reduction of tumor proliferation." (PMID 32423054, 2020). "MMP-2 and its inhibitors TIMP-1 and -2, also function in tumor invasion and metastasis." (PMID 32960785, 2020). "The goal of this study is to identify the CD63 binding motif of TIMP-1 that could be targeted to inhibit TIMP-1-mediated oncogenic signal transduction while preserving its tumor suppressive MMP-inhibitory functions." (PMID 32034211, 2020). "In addition, the tumor-derived cytokines CXCL1, CCL3, CXCL2, TIMP-1, and TNF-α, which have been implicated in the generation, migration, and activation of MDSCs at the tumor site, were regulated by the modulation of MDSCs." (PMID 33091036, 2020).